CXCL1 (C-X-C motif chemokine ligand 1)
Diseases named in the same sentence as CXCL1 in open-access papers (continued):
Sharing a sentence is not in itself a finding about the gene and the disease.
colitis (continued). "Otherwise, PGE2 has been demonstrated to induce CXCL1 and CXCL2 expression in the colonic mucosa and tumors, which leads to the chemoattraction of MDSC and promotes the colitis-associated tumorigenesis." (PMID 34689842, 2021). "In brief, pneumonia, liver injury, and colitis models demonstrate that the chemokine CXCL1 is strongly correlated with the recruitment of neutrophils." (PMID 34336855, 2021). "RT‐PCR and IHC analysis validated that TOE up‐regulated the expression of Adh5, Aldh3a2 and Acox3, but down‐regulated the expression of CCL20, CXCL5, CCR6 and CXCL1 in DSS‐induced colitis." (PMID 31565850, 2019). "The importance of CCL7, CCL8, CCL12, and CXCL1 to mediate colitis inflammation, and the consequence of enhanced monocyte expression of these chemokines on pathology, is not known." (PMID 30542349, 2018). "We conclude that defective resolution of colitis in mice deficient of myeloid HIF signaling is more likely due to factors (e.g., SAAs, CXCL1, and LTB4) other than SPMs." (PMID 30455703, 2018). "Together, these data support the idea that VNS attenuates HMGB1 levels and affects the colonic immune response, mainly reducing IL-6 and CXCL1 production in oxazolone-induced colitis eventually leading to an improved survival." (PMID 29791477, 2018). "In fact, as in TNBS-induced colitis, VNS reduced the serum levels of pro-inflammatory cytokines, i.e. IL-6, CXCL1, and TNFα, and dampened the colonic expression of IL-6 and CXCL1 in the oxazolone-induced colitis model." (PMID 29791477, 2018). "Our results clearly underline that H. polygyrus infection mediated colonic IL-6 and CXCL1 release facilitates aggravation of DSS-induced colitis." (PMID 28938014, 2017). "In contrast, H. polygyrus pre-infection in the RAG2-/- T cell transfer colitis model seems to induce IL-6 and CXCL1 in the colon in the same manner as in the DSS model." (PMID 28938014, 2017). "In summary, we conclude that H. polygyrus infection prior to DSS-induced colitis further enhances the inflammatory response in the colon based on enhanced IL-6 and CXCL1 expression and increased CD4+ T cell activation." (PMID 28938014, 2017). "To analyze if the helminth mediated increase in IL-6 and CXCL1 promoted the increased disease severity of DSS-induced colitis, we infected BALB/c mice with 200 third-stage larvae of H. polygyrus 6 days before DSS administration." (PMID 28938014, 2017). "DSS-colitis increased mRNA expression of interleukin IL-1a, IL-1b, IL-6, tumor necrosis factor TNFa, keratinocyte chemoattractant KC/CXCL1, granulocyte colony-stimulating factor, G-CSF and MCP-1." (PMID 27658624, 2016). "During the acute phase of colitis, the expression of several myeloid regulating cytokines/chemokines peaked in both genotypes, with higher levels of CXCL1 in colitic Eng+/− mice." (PMID 25114380, 2014). "C3a/C3aR thus appears to contribute to CXCL-1/KC mRNA production in acute DSS-induced colitis, and to augment neutrophil infiltration." (PMID 23638016, 2013). "Additionally, Rhy lowered serum levels of inflammatory cytokines IL-6, TNF-α, CXCL1, and IL-1β in colitis mice." (PMID 41031160, 2025). "Chemokine CXCL1 can have a pivotal role in promoting neutrophil infiltration in colitis." (PMID 40227242, 2025). "In fact, CXCL1−/− mice exhibited a great reduction in colitis after DSS treatment." (PMID 40227242, 2025). "However, we did observe higher expression of key inflammatory cytokines (Il6, Il1b, Il17b) and chemokines (Cxcl1 and Cxcl2) involved in colitis in wild-type compared to R38E-PAR2 mice." (PMID 39171684, 2024). "Taken together, these data support the notion that IL-22-mediated induction of neutrophil-active chemokines, including CXCL1 and CXCL5 is functionally important in the recruitment of CXCR2+ neutrophils, and that this pathway has an important pathogenic function in colitis." (PMID 36192482, 2022).
colitis (continued). "In addition, the plasma levels of granulocyte colony-stimulating factor (G-CSF), IL-6, IL-17, TNF-α, and chemokine ligand 1 (CXCL1) were significantly increased in the colitis model." (PMID 36009796, 2022). "After 7 days of induced colitis, upregulation of the expression of 22 genes (Ccl2, Ccl3, Ccl4, Ccl5, Ccl6, Ccl7, Ccl12, Ccl17, Cxcl1, Cxcl2, Cxcl6, Cxcl9, Cxcl11, Ccr1, Ccr2, Ccr3, Ccr5, Ccr8, Cxcr2, Csf3, Osm, and Spp1) was observed in the CβG− group compared to the HβG- control group." (PMID 35163326, 2022). "Similar to our observations in human UC, there was significant upregulation of the neutrophil-active chemokines Cxcl1, Cxcl2, Cxcl3 and Cxcl5 across all models of colitis tested, indicating that this core chemokine module is conserved in colitis development across species." (PMID 36192482, 2022). "To evaluate colitis severity, we measured the expression of different pro-inflammatory cytokines and chemokines and found that the same supplement suppressed the pro-inflammatory cytokines IL-6 and TNFα and the chemokines Cxcl1 and Ccl3." (PMID 34071180, 2021). "However, when the LSEC barrier is damaged, colitis-derived LPS can enter the liver sinusoids and lead to elevated CXCL1 expression by LSECs." (PMID 34336855, 2021). "We conclude that in addition to its known microbicidal action, cathelicidin has a unique pathogen-sensing role, facilitating LPS-mediated intestinal responses, including the production of CXCL8/CXCL1 that would contribute to an integrated tissue response to recruit neutrophils during colitis." (PMID 32658599, 2020). "Moreover, H. polygyrus infection in the course of dextran sulfate sodium (DSS) mediated colitis significantly exacerbates intestinal inflammation by amplifying the release of colonic IL-6 and CXCL1." (PMID 28938014, 2017). "Interestingly, treatment with bismuth significantly improved the colitis scores in A. parvulum-colonized mice and prevented expression of Il1β, Il12p40 and Cxcl1 messenger RNA (mRNA)." (PMID 27876802, 2016). "Consistently, we found that the TTP KO mice treated with DSS displayed increased susceptibility to colitis, decreased colon length, and increased neutrophil infiltration and expression of pro-inflammatory cytokines such as TNF-α, IL-6, CXCL1, and CXCL2 in the large intestinal mucosa." (PMID 24586391, 2014). "In contrast, pre-treatment with Bb-CM by i.p. route induced a significant protection against colitis (WS = 1.7±0.8, 62% protection) and a statistically significant decrease in pro-inflammatory cytokine expression [IL-1β, CXCL1 (equivalent to human IL-8), COX2, IL-23, IL-6]." (PMID 19381276, 2009). "Furthermore, VDUP1-KO mice exhibited increased mRNA expression of macrophage-attractive chemokines, including C-C motif chemokine ligand 2 (CCL2/MCP-1), C-C motif chemokine ligand 3 (CCL3/MIP1A), and keratinocyte chemoattractant (KC/CXCL1) in mice with DSS-induced colitis compared to WT mice." (PMID 37686390, 2023). "The results showed that acute and pre-remission stages of colitis were characterized by the increased gene expression of seven chemokines and four chemokine receptors in the colon wall as well as disrupted protein expression of CXCL1, CCL5, CXCR2, CCR5, and OPN in the mucosa." (PMID 35163326, 2022). "In accord with previous work, such blockade of IL-10 signaling resulted in typical features of colitis, including loss of weight/adiposity, splenomegaly, colomegaly, colon shortening, elevated MPO, increase in pathohistological scoring, and elevations in serum IL-6 and CXCL1." (PMID 31827095, 2019). "Development and remission of DSS-induced colitis in mice was determined by weight measurements and histology scores, and by quantification of expression of pro- (IL-1β, IL-6 and IFNγ) and anti-inflammatory (IL-10) cytokines, the chemokine CXCL1 and the inducible nitric oxide synthase." (PMID 24401855, 2014).
colitis (continued). "Nur77 can protect against experimental colitis by decreasing NF-kB activity, which in turn decreases the expressions of both MCP1 and CXCL1 in macrophages." (PMID 38666929, 2024). "The expression of CXCR2 and its ligands CXCL1 and CXCL5 was markedly lower in the PAI-1 KO group than in the WT (colitis) group following DSS treatment." (PMID 37151884, 2023). "The RNA array revealed that the CXC chemokines CXCL1 and CXCL5 and their common receptor CXCR2 were among the most significantly different genes between the PAI-1 KO mice with DSS-induced colitis and the WT mice." (PMID 37151884, 2023). "Next, we measured the expression levels of three selected cytokines, TNF-α, interleukin-6 (IL-6), and CXCL1/KC, in mouse serum to assess the possible anti-inflammatory effects of EVs on the DSS-induced colitis model." (PMID 37966243, 2023). "This was confirmed via TNBS-induced colitis, which showed that TNBS-induced acute Cxcl1 expression was considerably attenuated in Trim40−/− mice." (PMID 36755029, 2023). "Other cytokines assessed were for the most part unchanged other than IL-6, IL-22, and KC (CXCL1) which were likewise increased in plasma of both C57BL/6 and TCRδ-/- mice with DSS colitis indicative of systemic inflammation." (PMID 37063825, 2023). "The study showed that the protein expression of CXCL1 was significantly reduced after 3 and 7 days of TNBS-induced colitis." (PMID 35163326, 2022). "While A2BR signaling mediates glial upregulation of Il6 and downregulation of Csf3, Cxcl1, and Cxcl10, glial A2BRs in colon tissue mediated the DSS colitis-induced increase in protein expression of all these mediators." (PMID 35869148, 2022). "CXCL1 has been shown to mediate neutrophil recruitment by binding and activating CXCR2 expression on neutrophils during colitis in an M1-Toll-like receptor (TLR) signaling-dependent pathway." (PMID 35392084, 2022). "Furthermore, a rat model of DSS-induced colitis exposed to 8 mg/kg of deoxynivalenol in their diet for 4 weeks induced a more rapid and severe onset of colitis than controls and induced significant increases in pro-inflammatory markers (myeloperoxidase, CXCL-1, and IL-1β)." (PMID 33927703, 2021). "As for the colon, only three groups with DSS-induced colitis (aDSS, DSS + SOS, and DSS + SOS + LPSPn) showed increased CXCL1 and neutrophil infiltration in the colon." (PMID 34336855, 2021). "In the liver, CXCL1 expression and neutrophil recruitment are mainly triggered by the synergistic effect of DSS colitis + LSEC injury." (PMID 34336855, 2021). "In pneumonia, liver injury, and colitis models, the level of CXCL1 correlated with the recruitment of neutrophils in different tissues, while DSS colitis and LSEC injury synergistically contributed to increased CXCL1 expression in the liver." (PMID 34336855, 2021). "We have previously shown the anti-inflammatory effect of physical exercise; recreation led to reduced area of lesions and decreased expression of Il-1β (interleukin 1 beta), CXCL1 (C-X-C motif chemokine ligand 1), and MPO in a rat model of colitis." (PMID 31010141, 2019). "As in murine colitis, CCL7, CCL8, and CXCL1 were all significantly increased in active IBD vs. quiescent IBD and controls." (PMID 30542349, 2018). "A range of monocyte and neutrophil attracting chemokines (Ccl7, Ccl8, Cxcl1) were more highly expressed in macrophages compared to monocytes from both steady state and DSS colitis." (PMID 30542349, 2018). "The pro‐inflammatory cytokines IL1A, IL1B, IL6, and CSF3 and chemokines CXCL1 and CXCL2 were significantly increased, and the frequency of CD11b+Ly6G+ neutrophils was higher in CD11c‐Cre+Rab32f/f colitis mice." (PMID 30338217, 2018). "In line with the morphological appearance of colitis in the knockout mice, the expression of proinflammatory cytokines and chemokines, including IL6, IL1β, Cxcl1, and Ccl2, are dramatically increased in the colonic epithelial cells of the knockout mice." (PMID 28296893, 2017).
colitis (continued). "Lack of CLCA1 was associated with a more than two-fold increased expression of Cxcl-1- and Il-17-mRNA during DSS colitis." (PMID 26855614, 2016). "Our results showed that commensal bacteria induced the production of the chemokines CXCL1 and CXCL2, which induced the infiltration of Gr-1high/CD11bhigh neutrophils in the AOM/DSS-induced colitis." (PMID 27050089, 2016). "In summary, 2.0% DSS-induced colitis is accompanied by increased local colonic IFN-γ, GM-CSF, CXCL1 and IL-17 secretion in CD137−/− compared to WT mice." (PMID 24023849, 2013). "Other chemokines like CXCL1 and CXCL2, have previously been found up-regulated in TNBS-colitis and were up-regulated in our data." (PMID 23382912, 2013). "It has been shown that selective blockade of IL-1R, CXCR2, CXCL1/KC, MCP-1, MIP-2, TNF-α and IL-6 significantly decreases severity of colitis and neutrophil/macrophage migration." (PMID 22073270, 2011). "In contrast to our results, other studies indicate an anti-inflammatory role for 17 HDHA, with negative correlations observed with IL-1β and other cytokines and adhesion molecules such as TNF-α, MIP-2, CXCL1/KC, VCAM-1, ICAM-1, and LFA-1 in an animal model of colitis." (PMID 41009650, 2025). "In addition, DEGs associated with the immune receptor (Lrrc19), cell chemotaxis (Ccr7, Cxcl1, Cxcl5, Cxcl9, and Cxcl10), and inflammatory response (IL1r11, IL11, Tnf, IL1β, and IL18) were also upregulated in the colonic tissue of colitis mice in DVF group." (PMID 38172943, 2024). "Moreover, the intestinal cells have up-regulation of pro-inflammatory chemokines like C-X-C motif chemokine ligand (CXCL) 1 (CXCL1), CXCL3, and CXCL8, which only perpetuates the inflammatory cycle of colitis." (PMID 36677021, 2023). "The chemokines CXCL1 and CXCL2 and their receptor CXCR2 play an important role in experimental colitis because the deletion of CXCR2 alleviates chronic colitis and associated tumors by inhibiting the penetration of myeloid derived suppressor cells (MDSCs) into the colon mucosa." (PMID 35163326, 2022). "In PTENΔDC mice, we found elevated IL-6 serum levels, but no changes in IL-33 or CXCL-1 (also known as KC), which previously have been shown to be increased during colitis." (PMID 35514976, 2022). "Furthermore, there were increased levels of CXCL1 and the number of neutrophils in the peripheral blood in the groups containing LPS-induced pneumonia or DSS-induced colitis (including aDSS, LPSPn, SOS + LPSPn, DSS + SOS, and DSS + SOS + LPSPn)." (PMID 34336855, 2021). "Accordingly, we observed that the expression levels of genes encoding chemokines (Ccl3, Ccl4, and Ccl6), chemokine receptors (Ccr1, Ccr5, Cxcr2, Cxcl1, Cxcl2, and Cxcl13), and inflammatory factors (Mpo, Il-1β, and Il12) were increased in mice with DSS-induced colitis." (PMID 34795650, 2021). "Moreover, when DSS colitis was added (DSS + SOS + LPSPn group), hepatic neutrophils and CXCL1 were thus significantly increased." (PMID 34336855, 2021). "This further demonstrated that DSS colitis and LSEC barrier damage could synergistically contribute to hepatic CXCL1 expression, which further promoted the recruitment of neutrophils into the liver." (PMID 34336855, 2021). "In the current study, we detected a significantly higher colonic expression of Ccl2, Cxcl1, Cxcl2, and Cxcr3 genes in the control and RB groups (p < 0.05, RB vs. control) compared to the FRB group, which supports the protective effect of FRB in colitis." (PMID 28703759, 2017). "Lamina propria macrophages of EPRAP-deficient mice exhibited marked increases in the mRNAs corresponding to TNF-α, IL-1β, IL-6, CXCL1, and MCP-1 relative to those of WT mice, indicating that EPRAP contributes critically to inhibiting macrophage activation and colonic inflammation." (PMID 26439841, 2015). "In addition, the mRNA expression of several cytokine/chemokine (IL-6, CXCL1, CCL11, and IL-1β) genes was low in Eng+/− mice at days 18–23 of colitis." (PMID 25114380, 2014).
colitis (continued). "Furthermore, the slight rise of pro-inflammatory factors like IL-6, CXCL1, and CXCL2 might suggest possible spontaneous colitis in a long observation period." (PMID 36425784, 2022). "In an initial experiment using the streptomycin pre-treated C57bl/6 mouse model of colitis we found that mice infected with randomly selected strains of the same phylogroup (ST34 or U288) exhibited similar colonisation level, induction of Cxcl1 (KC) and Nos-2 (iNOS) and intestinal pathology." (PMID 33893390, 2021). "A 16-gene signature (CARD12, CCL3, CCR3, CXCL1, F5, FAM210B, GADD45A, IL18bp, IL2RA, IL5, IL8, MMP9, PTGS2, SOCS3, TLR9 and UBE2C) was identified from 30 days post-tremelimumab initiation blood that discriminated patients developing grade 0–1 from grade 2–4 diarrhea/colitis." (PMID 30227886, 2018). "However, as compared with the SOS group, the DSS + SOS group had significantly increased hepatic neutrophils and liver CXCL1 expression, which indicated that when the LSEC barrier was damaged, DSS colitis might lead to the recruitment of hepatic neutrophils via CXCL1." (PMID 34336855, 2021). "The absence of GPR4 ameliorates colitis with lower histology scores, reduced CD4+ T helper cell infiltration, and decreased IFN-γ, iNOS, CXCL1, and CXCL2 expression." (PMID 35165253, 2022).